MIAT (myocardial infarction associated transcript)
Synonyms: FLJ25967; Rncr2; gomafu; NCRNA00066; LINC00066; lncRNA-MIAT; C22orf35
Gene: Long non-coding RNA gene on chromosome 22 (26,646,411 to 26,676,478, forward strand). Ensembl gene ENSG00000225783.
Gene Ontology:
Biological process: cell fate specification
Cellular component: nucleus
Diseases named in the same sentence as MIAT in open-access papers:
MIAT is named in the same sentence as 138 diseases in open-access papers, as found by Europe PMC text mining. Sharing a sentence is not in itself a finding about the gene and the disease. The quoted sentences say what the papers report.
myocardial infarction (95 papers, 2011 to 2026). Gross necrosis of the myocardium, as a result of interruption of the blood supply to the area, as in coronary thrombosis. "The myocardial infarction-associated transcript (MIAT), a conserved long noncoding RNA, is upregulated in failing human and murine hearts." (PMID 41764204, 2026). "Among these, the myocardial infarction-associated transcript (MIAT) has emerged as a significant contributor to cardiac damage." (PMID 41245486, 2025). "Myocardial infarction-associated transcript (MIAT), a long non-coding RNA upregulated in failing hearts, inhibits microRNA-150 (miR-150), which typically suppresses HOXA4 expression." (PMID 41181801, 2025). "MIAT has been directly associated with myocardial infarction (heart attack) and is reported to regulate post-transcriptional processes by acting as a ceRNA, competing with other RNA molecules for shared miRNA binding sites." (PMID 39920595, 2025). "Altered expression of MIAT is implicated in cellular apoptosis and the pathogenesis of several diseases, including myocardial infarction, microvascular dysfunction, diabetes, and cancer." (PMID 40282196, 2025). "Myocardial infarction associated transcript (MIAT) is a lncRNA, whose potential protective role in DR has been identified." (PMID 38202299, 2024). "Genome-wide association studies (GWASs) illustrated that MIAT rs2331291 in intron 15,338 is related to altered vulnerability to myocardial infarction." (PMID 38255915, 2024). "later found MIAT is located within a susceptible locus for myocardial infarction (MI), leading them to name this novel gene as MIAT." (PMID 39379100, 2024). "Our recent findings revealed increased expression levels of the lncRNAs XIST (X-inactive specific transcript) and MIAT (myocardial infarction-associated transcript) in leiomyomas." (PMID 38279317, 2024). "MIAT was identified in a large-scale case-control study, and is a myocardial infarction susceptibility locus found on chromosome 22q12.1." (PMID 39135912, 2024). "Recently, a cross-sectional study concluded that circulating MALAT1 (metastasis-associated lung adenocarcinoma transcript 1) and MIAT (myocardial infarction-associated transcript) were promising predictors for blood transfusion status in β-thal patients." (PMID 38165465, 2024). "Specifically, MIAT has been identified as a myocardial infarction susceptibility locus in a large-scale case-control study, and is also implicated in diabetic retinopathy, microvascular dysfunction, and neuronal development." (PMID 39135912, 2024). "Knockdown of MI-triggered upregulation of endogenous MIAT (myocardial infarction-associated transcript) reduced cardiac fibrosis and improved cardiac function via the regulation of the miR-24/furin-TGFβ-1 pathway." (PMID 37504569, 2023). "GOMAFU was initially identified in mouse retinal cells as retinal non-coding RNA 2 (Rncr2) as well as in myocardial infarction patients, termed myocardial infarction associated transcript (MIAT)." (PMID 35741078, 2022). "An example of a well-known ceRNA orchestrated by a lncRNA is the overexpression of MIAT (myocardial infarction-associated transcript) in myocardial infarction." (PMID 36289882, 2022). "The aberrant expression of lncRNA myocardial infarction-associated transcript (MIAT), which is mainly expressed in the heart, was firmly associated with apoptosis, cell proliferation, and fibrotic remodeling in acute myocardial infarction." (PMID 35269870, 2022). "LncRNA myocardial infarction-associated transcript (MIAT) was originally isolated as a candidate gene for myocardial infarction." (PMID 35782387, 2022). "MIAT is also an important lncRNA that was first found to be associated with myocardial infarction and later it was found to be involved in the progression of tumours, including retinoblastoma, smooth muscle tumour, and nasopharyngeal carcinoma." (PMID 36384476, 2022).
myocardial infarction (continued). "MIAT, also known as RNCR2 or Gomaful8,91, is one of the long non-coding RNAs associated with myocardial infarction discovered early, which is located on human chromosome 22q12.1 with a length of 30051 bp." (PMID 36275741, 2022). "Myocardial infarction associated transcript (MIAT) is a long non-coding RNA that have key-role in several diseases, including myocardial infarction." (PMID 35413811, 2022). "We identified an increased expression of the lncRNA DNM3OS (DNM3 antisense RNA) and MIAT (Myocardial infarction associated transcript) from these analyses." (PMID 35237874, 2022). "MIAT (myocardial infarction associated transcript; also known as GOMAFU, LINC00066, RNCR2) is lncRNA encoded by 30,051 bp long intergenic region located on 22q12.1." (PMID 36362925, 2022). "lncRNA myocardial infarction associated transcript (MIAT) has a protective effect against the ox-LDL-induced apoptosis through inhibiting miR-181b and signal transducer and activator of transcription 3 (STAT3)." (PMID 34552965, 2021). "Several lncRNAs, namely, myocardial infarction-associated transcript (MIAT), H19, and metastasis-associated lung adenocarcinoma transcript 1 (MALAT1), have also been reported to be altered in AMI patients, but studies in this regard are still in their infancy." (PMID 34063483, 2021). "MIAT (myocardial infarction associated transcript), also known as RNCR2 (retinal non‐coding RNA 2), is a lncRNA that is involved in various diseases, such as myocardial infarction, diabetic complications, ischaemic stroke and cancers." (PMID 34687132, 2021). "Myocardial infarction-associated transcript (MIAT), previously known as RNCR2 (retinal non-coding RNA2) and GOMAFU, was first identified as lncRNA in the study of susceptibility of myocardial infarction." (PMID 32210708, 2020). "MIAT (myocardial infarction associated transcript) was the first lncRNA identified by GWAS as a disease candidate gene." (PMID 32754192, 2020). "lncRNA myocardial infarction-associated transcript (MIAT) was found remarkably increased in PC tissues and cell lines, and PC patients with high MIAT levels had poor prognosis than those with low MITA levels." (PMID 32850392, 2020). "By comparing the co-expression with ceRNA networks, five lncRNAs (SNHG9, LINC02202, UBAC2-AS1, PTCSC3 and myocardial infarction associated transcript (MIAT)) and 32 genes (such as PIK3R1, PTPRB) were found to be shared." (PMID 31534842, 2019). "Another endothelial cell lncRNA, MIAT (Myocardial Infarction Associated Transcript), was previously associated with myocardial infarction in a large genetic study of a Japanese population." (PMID 30838214, 2019). "Recent studies reported that a few lncRNAs, including H19, metastasis-associated lung adenocarcinoma transcript 1 (MALAT1), and myocardial infarction-associated transcript (MIAT), were involved in the pathogenesis of DCM in type 1 diabetic animals." (PMID 31653946, 2019). "Myocardial infarction associated transcript (MIAT) was originally identified as a candidate gene for myocardial infarction, and recently shown to participate in the progression of cancer and the process of metastasis, such as melanoma." (PMID 31649871, 2019). "We found that myocardial infarction–associated transcript (MIAT) was significantly upregulated in diabetic rats." (PMID 28703801, 2017). "We previously established a rat model of diabetic cardiomyopathy (DCM) and found that the expression of long non-coding RNA myocardial infarction–associated transcript (MIAT) was significantly upregulated." (PMID 28703801, 2017). "Myocardial infarction associated transcript (MIAT), also known as Gomafu or retinal ncRNA 2 (RNCR2), was first indicated as a susceptibility locus for myocardial infarction and found to be highly expressed in retinal precursor cells." (PMID 29074557, 2017). "MIAT, originally isolated as a candidate gene for myocardial infarction, encodes lncRNA (termed MIAT)." (PMID 27527866, 2016).
myocardial infarction (continued). "Next, the long noncoding RNA RNCR2 (retinal non-coding RNA 2), synonym of MIAT (myocardial infarction associated transcript), plays a critical role in regulating mammalian retinal cell fate specification." (PMID 26459019, 2015). "Another lncRNA, MIAT (myocardial infarction-associated transcript) (or Gomafu/RNCR2) was identified as a risk factor associated with patients with myocardial infarction." (PMID 25153164, 2014). "A large scale case-control association study regarding cardiovascular disease demonstrates that a MIAT variant (rs2301523) confers susceptibility to myocardial infarction." (PMID 24113581, 2013). "Furthermore, miR-147a directly interacts with myocardial infarction-associated transcript (MIAT), and E2F transcription factor 3 (E2F3) has been established as the target gene of miR-147a." (PMID 40282196, 2025). "MIAT is located on the 22q12.1 locus associated with myocardial infarction susceptibility." (PMID 38202299, 2024). "LncRNA MIAT (myocardial infarction associated transcript) or RNCR2 (retinal non-coding RNA 2) (Ref." (PMID 39320855, 2024). "Myocardial infarction-associated transcript (MIAT) encodes a spliced lncRNA that may constitute a component of the nuclear matrix." (PMID 36620092, 2022). "Altered expression of MIAT is associated with the susceptibility to myocardial infarction." (PMID 36620092, 2022). "MIAT is a lncRNA that was initially identified to be associated with myocardial infarction, but recent studies have implicated that MIAT is also involved in paranoid schizophrenia, diabetes-related diseases, neurovascular dysfunction, cardiac hypertrophy, and cancer." (PMID 34811354, 2021). "Moreover, the large-scale case–control association studies have identified a novel myocardial infarction-associated transcript, MIAT (also termed LINC00066), which encompasses rs2331291, and other variants confer the susceptibility of myocardial infarction." (PMID 32523949, 2020). "In addition, another study showed that the expression level of MIAT in peripheral blood cells of patients with acute myocardial infarction (AMI) is regulated after AMI and associated with prognosis." (PMID 32969576, 2020). "Analysis of serum from atherosclerosis patients has shown upregulation of myocardial infarction-associated transcript (MIAT) expression and inverse regulation of miR-181b expression who were revealed that block cell growth, induce cell cycle arrest, impede proliferation and promoting apoptosis." (PMID 31942979, 2020). "Among which, Myocardial Infarction Associated Transcript (MIAT) encodes a spliced lncRNA that may constitute a component of nuclear matrix, and altered expression of this molecule is reported to be associated with susceptibility to myocardial infarction." (PMID 32549789, 2020). "Two lncRNAs, myocardial infarction-associated transcript(MIAT) and metastasis-associated lung adenocarcinomatranscript 1 (MALAT1), may be involved in the pathogenesis ofcoronary artery disease (CAD)." (PMID 31188931, 2019). "Functional analysis pointed out that the fifth exon mutation induced an increase in LncRNA-MIAT transcription, suggesting that changes in the expression of MIAT may play an important regulatory role in myocardial infarction." (PMID 31143478, 2019). "Originally identified within a susceptible locus for myocardial infarction on chromosome 22q12.1, MIAT was then characterized as the RNA component of specific nuclear bodies where it may affect RNA splicing, ultimately regulating gene expression." (PMID 29700321, 2018). "Myocardial infarction associated transcript (MIAT), which was recently found to demonstrate aberrant expression in various diseases, such as myocardial infarction, schizophrenia, ischemic stroke, diabetic complications, age-related cataract and cancers, is a novel disease-related lncRNA." (PMID 29534728, 2018). "For example, the expression of myocardial infarction associated transcript (MIAT) was lower." (PMID 27667091, 2016).
myocardial infarction (continued). "Long intergenic non-coding RNA predicting cardiac remodeling (LIPCAR), uc004cos.4, uc004cov.4, uc004coz.1, uc011mfi.2, uc022bqu.1, uc022bqw.1, HOX transcript antisense RNA (HOTAIR) and myocardial infarction-associated transcript (MIAT) were consistently amplified in all individual samples." (PMID 27874027, 2016). "Interestingly, single nucleotide polymorphisms in the human homologue of Gomafu are associated with an increased risk of myocardial infarction, and thus the gene has been named myocardial infarction associated transcript (MIAT)." (PMID 21463453, 2011). "The lincRNA Myocardial Infarction Associated Transcript (MIAT) is associated with a genetic susceptibility towards myocardial infarction (MI)." (PMID 35784351, 2022). "The human GOMAFU is produced from the MIAT gene, which was identified on chromosome 22q12.1 within a susceptibility locus for myocardial infarction (MI)." (PMID 35741078, 2022). "Myocardial infarction-associated transcript (MIAT; also referred to as RNCR2, Gomafu, or AK028326) was originally identified in a case-control GWAS, where 6 SNPs in the MIAT locus conferred susceptibility to myocardial infarction (MI)." (PMID 31337130, 2019). "Myocardial infarction associated transcript (MIAT) was identified as a susceptible locus for MI in a Japanese population by large-scale case-control associated study." (PMID 30619888, 2018). "They discovered a cDNA of new gene within the genome, named myocardial infarction associated transcript (MIAT), and six SNPs of MIAT may confer genetic risk for MI." (PMID 40520644, 2025). "Lentivirus-mediated systemic knockdown of MIAT in rodents improved cardiac function and structure in post-MI and in diabetic hearts as well as reduced ischemia/reperfusion (I/R)-induced myocardial infarct size and apoptosis." (PMID 39979325, 2025). "Another example of PROX1 regulation by miRNA sponging is provided by the lncRNA myocardial infarction‐associated transcript (MIAT), also known as RNCR2 or Gomafu." (PMID 37407839, 2023). "Another prominent lncRNA involved in the pathogenesis of DR is myocardial infarction-associated transcript (MIAT; also referred to as RNCR2, Gomafu, or AK028326)." (PMID 35464068, 2022). "Emerging data suggest that MIAT, a novel lncRNA related to myocardial infarction, is important for cardiomyocyte survival and apoptosis, as well as regulation of cardiac function under pathophysiological conditions." (PMID 35186188, 2022). "Several lncRNAs play an important role in cardiovascular diseases, such as lncRNA LIPCAR "dysregulation in heart failure and lncRNA MIAT upregulations in myocardial infarction." (PMID 36617651, 2022). "Silencing MIAT significantly decreased apoptosis and increased ATP production in cardiomyocytes, thus alleviating the impairment of cardiac function after myocardial infarction." (PMID 35186188, 2022). "ALKBH1 decreased the m6A modification of the myocardial infarction associated transcript (MIAT) promoter region, which allowed HIF-1α binding to this site to upregulate the transcripts of lnc-MIAT." (PMID 34869371, 2021). "MIAT (RNCR2) is a lncRNA that aberrant expression was observed in many human diseases, including myocardial infarction, schizophrenia, ischemic stroke, diabetic complications, age-related cataract, and cancer." (PMID 34502084, 2021). "Recently, it has been found that MIAT can participate in multiple diseases, such as microvascular dysfunction, myocardial infarction and cancers." (PMID 33009725, 2020). "MIAT expression was also significantly higher in mice heart in response to I/R injury, which was correspondent to increased myocardial infarct size and decreased heart function." (PMID 30971184, 2019). "Dysregulated MIAT was first reported to correlated with myocardial infarction and involved in cardiac hypertrophy and diabetic cardiomyopathy." (PMID 31795964, 2019).
myocardial infarction (continued). "Our findings are in line with several previous studies which showed that targeting MIAT significantly improved cardiac function and reduced myocardial infarction size in different myocardial I/R animal models." (PMID 30971184, 2019). "MIAT is involved in various cellular processes, including myocardial infarction, microvascular dysfunction, paranoid schizophrenia, nuclear body formation, and neurogenic commitment." (PMID 29228680, 2017). "MIAT was first identified as a candidate gene for myocardial infarction; it is abundantly expressed in the nervous system and retinal tissue." (PMID 29228680, 2017). "MIAT/RNCR2, originally discovered as a candidate gene for myocardial infarction, is a lncRNA abundantly expressed in nervous system and retinal tissue." (PMID 27527866, 2016). "For example, MIAT was abundantly expressed in myocardial infarction." (PMID 35186188, 2022). "For example, MIAT is involved in myocardial infarction and microvascular dysfunction." (PMID 35282774, 2022). "In nonsmall-cell lung cancer, C-containing genotypes of MIAT rs1061451 were found to be protective factors in NSCLC, and myocardial infarction associated transcript (MIAT), which may act as a ceRNA via miR-133a-5p, modulated the SGK1 expression level." (PMID 33542904, 2020). "In addition, MIAT was shown to be involved in a number of diseases, such as myocardial infarction, diabetic retinopathy, microvascular dysfunction, and paranoid schizophrenia." (PMID 29914974, 2018). "Among the down-regulated lncRNAs, HAR1A (highly accelerated region 1A) and MIAT (myocardial infarction associated transcript) were presented with high value of an absolute log2(fold-change) (logFC =-2.873, P =2.98E-11 for HAR1A; logFC =-2.459, P =1.61E-07 for MIAT)." (PMID 29108264, 2017). "Similarly, MIAT (myocardial infarction associated transcript) is a non-protein coding gene, and the relevance of these transcripts in T cell differentiation is not understood, yet." (PMID 23110343, 2012). "We discovered targeting MIAT remarkably enhanced H9c2 cell viability, decreased H/R-induced cell apoptosis and LDH leakage and significantly decreased I/R-induced myocardial infarct size, reduced myocardial apoptosis and enhanced the heart function." (PMID 30971184, 2019). "Moreover the regulation operated by ncRNA might confer susceptibility to various diseases: e.g., a myocardial infarction-associated transcript (MIAT), also known as RNCR2 or Gomafu, is a long intergenic non-coding RNA that presents many genetic variants implicated in different processes." (PMID 24113581, 2013). "Myocardial infarction-associated transcript (MIAT), also known as retinal noncoding RNA 2 (RNCR2), has been known to associate with myocardial infarction." (PMID 34199672, 2021). "The myocardial infarction-associated transcript (MIAT, also known as retinal non-coding RNA2, RNCR2) is an abundant lncRNA with a punctuate distribution in the nucleoplasm." (PMID 34502084, 2021). "Myocardial infarction-associated transcript (MIAT), also known as retinal noncoding RNA 2 (RNCR2), is identified in myocardial infarction." (PMID 30891461, 2019).